ZBTB22 (zinc finger and BTB domain containing 22)
Description:
May be involved in transcriptional regulation.
Synonyms: BING1; ZBTB22A; ZNF297; ZNF297A; fruitless; fru
Tractability: No criterion of Open Targets' tractability assessment is met for any kind of drug.
Safety:
Unwanted effects reported when the protein is acted on. In parentheses: how it was acted on, where the effect was seen, and who reports it.
asthma (source: ClinPGx)
Gene: Protein-coding gene on chromosome 6 (33,314,406 to 33,318,021, reverse strand). Ensembl gene ENSG00000236104.
Subcellular location: Nucleus
Subcellular location (Human Protein Atlas): Nucleoplasm
Gene Ontology:
Molecular function: protein binding; sequence-specific double-stranded DNA binding; DNA binding; DNA-binding transcription factor activity, RNA polymerase II-specific; RNA polymerase II cis-regulatory region sequence-specific DNA binding
Biological process: regulation of transcription by RNA polymerase II
Cellular component: chromatin; nucleus
Genetic constraint (gnomAD): Loss-of-function variants: 0 observed, 1.44 expected, observed/expected ratio (o/e) 0, 90% interval 0 to 1.58. That is too few expected variants to judge how well the gene tolerates losing a copy. Missense variants: 668 observed, 879.08 expected, observed/expected ratio (o/e) 0.76, 90% interval 0.71 to 0.81. Synonymous variants: 356 observed, 368.6 expected, observed/expected ratio (o/e) 0.97, 90% interval 0.88 to 1.05.
Homologues: Orthologues: chimpanzee ZBTB22 (99% identical), macaque ZBTB22 (98% identical), dog ZBTB22 (93% identical), pig ZBTB22 (92% identical), guinea pig ZBTB22 (88% identical), mouse Zbtb22 (86% identical), rat Zbtb22 (86% identical), tropical clawed frog zbtb22 (44% identical), zebrafish zbtb22b (41% identical), zebrafish zbtb22a (28% identical). Paralogues in human: ZBTB9 (27% identical), ZBTB10 (16% identical), ZBTB8B (15% identical), ZBTB8A (14% identical), C17orf113 (11% identical).
Diseases named in the same sentence as ZBTB22 in open-access papers:
ZBTB22 is named in the same sentence as 1 disease in open-access papers, as found by Europe PMC text mining. Sharing a sentence is not in itself a finding about the gene and the disease.
ZBTB22 shares sentences with these, for which no sentence is quoted: cancer (1 paper).